ETV1 (ETS variant transcription factor 1)
Diseases named in the same sentence as ETV1 in open-access papers (continued):
Sharing a sentence is not in itself a finding about the gene and the disease.
prostate carcinoma (continued). "Using this approach, it was reported that the inhibitor of the EWS-FLI1 oncoprotein in Ewing’s Sarcoma (YK-4-279) can downregulate the gene expressions of ERG and ETV1 downstream target genes in ETV1 or ERG fusion-positive prostate cancer cells." (PMID 24739220, 2014). "We recently demonstrated that the small molecule YK-4-279 inhibits biological activity of ETV1 in fusion-positive prostate cancer cells leading to decreased motility and invasion in-vitro." (PMID 25479232, 2014). "We recently reported that YK-4-279, an inhibitor of EWS-FLI1 oncoprotein in Ewings sarcoma, also inhibits ERG and ETV1 activity in prostate cancer cells in-vitro, resulting in reduced migratory and invasive phenotypes." (PMID 25479232, 2014). "Translocations involving ERG and ETV1 constitute the majority of ETS rearrangements found in prostate cancer." (PMID 25479232, 2014). "It is curious to note that a small fraction of prostate cancers have translocations of the ETV1 gene (a member of the Ets family of transcription factors) into HERV-K loci." (PMID 24204631, 2013). "Recent experiments from our group have also indicated that YK-4-279 is able to inhibit ERG and ETV1 fusion-positive prostate cancer cell lines, and the activity and function of the enantiomers should be further investigated in prostate cancer." (PMID 22383402, 2012). "A similar pattern was observed in prostate cancer: the complete exon-1 of TMPRSS2 was identified to fuse with ETV1 or ERG as one of the most recurrent rearrangements." (PMID 22496636, 2012). "Some well-established fusion genes have also been shown to be promiscuous, examples including MLL- in leukemias, EWS- in sarcomas, RET- in carcinomas and TMPRRS2- and ETV1-fusions in prostate cancer." (PMID 23119097, 2012). "In this study we describe the genetic background of full-length ETV1 overexpression and the biological properties of different full-length ETV1 isoforms in prostate cancer." (PMID 21298110, 2011). "Fusions of TMPRSS2 and three other genes encoding ETS transcription factors, ETV1, ETV4 and ETV5, which are located on different chromosomes, occur at low frequency in prostate cancer." (PMID 21298110, 2011). "Little is known about the mechanism of full-length ETV1 overexpression and its function in clinical prostate cancer." (PMID 21298110, 2011). "ETV1 is overexpressed in a subset of clinical prostate cancers as a fusion transcript with many different partners." (PMID 21298110, 2011). "Following ERG, ETV1 is the most frequently overexpressed ETS gene in prostate cancer (∼10% of the tumors)." (PMID 21298110, 2011). "The discovery of ERG/ETV1 gene rearrangements and PTEN gene loss warrants investigation in a mechanism-based prognostic classification of prostate cancer (PCa)." (PMID 20104229, 2010). "We have used a fluorescence in situ hybridisation (FISH) ETV1 gene ‘break-apart’ assay to screen for ETV1 rearrangements on a Tissue Microarray (TMA) consisting of 945 trans-urethral resection of the prostate cancer cores from 429 patients." (PMID 18594527, 2008). "A fluorescence in situ hybridisation (FISH) assay has been used to screen for ETV1 gene rearrangements in a cohort of 429 prostate cancers from patients who had been diagnosed by trans-urethral resection of the prostate." (PMID 18594527, 2008). "Lastly, ETV1/ER85, a partner in the high frequency TMPRSS2:ETV1 chromosomal fusion event in human prostate cancer, is a downstream target of RAS-RAF-MAPK signaling." (PMID 19079609, 2008). "The reported incidence of TMPRSS2:ETV1 fusion in these studies (1–2%) was, however, considerably lower than the observed incidence of ETV1 gene overexpression (∼10% in prostate cancer)." (PMID 18594527, 2008). "Classic regulators of epithelial‐mesenchymal transition (EMT), such as TWIST1, vimentin or N‐cadherin, have also been identified as ETV1 target genes involved in cell invasion induced by this transcription factor particularly in colorectal and prostate cancers." (PMID 40275610, 2025).
prostate carcinoma (continued). "At present, there are lots of studies on ETV1 in prostate cancer." (PMID 39668941, 2025). "Cotargeting EGFR and STAT3 with Erlotinib and TTI‐101 impairs both 2D and 3D growth of ETV1‐overexpressing prostate cancer cells by disrupting a self‐sustaining ETV1–EGFR positive feedback loop that promotes EGFR and STAT3 expression and phosphorylation (activation)." (PMID 40808640, 2025). "ETV1 is an oncogenic driver in cancers, like prostate cancer and Ewing’s sarcoma." (PMID 38388484, 2024). "Nuclear function of β-DG may contribute to prostate cancer; because nuclear import of tyrosine-phosphorylated β-DG results in activation of the oncogenic transcription factor ETS variant 1 (ETV1)." (PMID 39115711, 2024). "miR-129-5p was identified to decreased in prostate cancer and may function as a tumor suppressor via repression of ETV1." (PMID 38446257, 2024). "Thus, deregulation of Dach1 alone, like deregulation of CHD, ERG1, or ETV1, is insufficient to drive prostate cancer in the mouse prostate." (PMID 37095257, 2023). "Targeting ETV1 in CIC and ERF-deficient prostate cancer limits tumor growth." (PMID 36383412, 2022). "In this light, it has been found that disruption of ETV1 expression (by siRNA transfection) strongly compromises the invasive capacity of both androgen-dependent (LNCaP) and -independent (C81) cells, suggesting that ETV1 plays an important role in prostate cancer metastasis." (PMID 36494657, 2022). "In addition, androgen and genotoxic stress recruit cytidine deaminase (AID) and LINE1-encoded ORF2 endonuclease to the specific sites and induce DNA cleavage of TMPRSS2, SLC45A3, ERG, and ETV1 in prostate cancer." (PMID 36579559, 2022). "Interestingly, the transcriptional role of ERG described by Yu and colleagues is in contrast with ETV1 transcriptional activity in prostate cancer." (PMID 33634124, 2021). "Our lab has previously identified Ets Variant 1 (ETV1), a member of the PEA3 subfamily, as a novel androgen-regulated gene that is involved in prostate cancer cell invasion through unknown mechanism." (PMID 32296610, 2020). "Indeed, among the four members of the PEA3 family of transcription factors, only ETV1 is expressed and exhibits androgen-inducible expression in prostate cancer cells." (PMID 32296610, 2020). "Our data here clearly demonstrate both endogenous and exogenous ETV1 can promote expression of Twist1 in prostate cancer cells, and this ETV1 positive effect was also observed on a Twist1-Luc reporter plasmid, which is a consistent with a direct effect of ETV1 on the Twist1-promoter." (PMID 32296610, 2020). "To test this, we utilized human PC3 prostate cancer cells, which express high levels of endogenous ETV1 and are not deficient in TGF-β signaling." (PMID 31160676, 2019). "Conversely, we found that ETV1 may enhance TGF-β signaling in PC3 prostate cancer cells, revealing a different facet of the ETV1/TGF-β interplay." (PMID 31160676, 2019). "ETV1 is a known fusion partner in prostate cancer with upstream genes like SLC45A311." (PMID 31537872, 2019). "In addition, a small molecule inhibitor of ETV1 suppressed prostate cancer cell proliferation in vitro and in vivo." (PMID 31160676, 2019). "In some prostate cancer cases, a translocation of the HERV-K_22q11.23 5′-LTR-UTR sequence upstream of the transcription factor ETS translocation variant 1 (ETV1) has been described, which results in the enhanced expression of the ETV1 oncogene promoting cancerogenesis." (PMID 29487579, 2018). "In addition to recurrent FOXA1 forkhead domain mutations, the 14q21.1 region is also a recurrent partner in ETV1-activating structural rearrangements in prostate cancer." (PMID 30272002, 2018). "Additionally, ETS variant 1 (ETV1) and fatty acid synthase (FASN) mRNAs identified in LNCaP- and PC-3- derived MVs highly correlated with prostate cancer progression." (PMID 28143451, 2017).
prostate carcinoma (continued). "In an analysis of 333 individual prostate cancer exomes, TCGA identified seven subtypes defined either by gene fusions involving the ETS family (59% of cases), specifically ERG, ETV1, ETV4, or FLI1, or recurrent mutations (15% of cases) in SPOP, FOXA1, or IDH1." (PMID 28423598, 2017). "Evaluation of the altered pathways showed that AR, IGF1, IGFBP5 and ETV1 were markedly decreased in the AfA derived cell line compared with CaA cells, and there was a reciprocal regulatory relationship of miR-24/target expression in prostate cancer patients." (PMID 28157714, 2017). "Taken together, these data support the hypothesis that targeting TYK2 and/or MST1 with specific inhibitors could be a useful approach in the blockage of prostate cancer progression in ETV1- positive PCa." (PMID 26097883, 2015). "Interestingly, our group has recently shown that the ETS transcription factors ERG and ETV1 are able to regulate both specific and shared sets of genes in prostate cancer cells." (PMID 25595908, 2015). "Ets overexpression may follow chromosome rearrangements, from copy gains of ETV1 in melanoma, to fusion of ERG or ETV1 to the TMPRSS2 promoter, resulting in androgen-inducible expression in prostate cancer, associated with aggressive disease." (PMID 24450640, 2014). "Its function in prostate cancer lies in the overexpression of E26 transformation-specific (ETS) transcription factors, such as ETS-related gene (ERG) and ETS translocation variant 1 (ETV1) through gene fusion." (PMID 24877145, 2014). "Where transcriptional changes could be validated by qPCR, ETV1 stood out as a strong candidate for a role in dystroglycan mediated modulation of prostate cancer progression." (PMID 24077328, 2013). "Furthermore oncogenic ETV1 can mimic Ras/MAPK signalling in prostate cancer leading to increased cell migration." (PMID 24077328, 2013). "However, a unique characteristic of ETV1 is that it can not only be overexpressed in prostate cancer as a fusion transcript but also as a full-length wild-type transcript." (PMID 21298110, 2011). "In addition, with the possible exception of ETV1, whose prevalence of overexpression was about 2-fold higher in the SYS cases, none of the genes seemed to be associated with systemic progression of prostate cancer." (PMID 18846227, 2008). "Tomlins and colleagues (2005) identified recurrent gene fusions of TMPRSS2 to two ETS transcription factors, ERG and ETV1, and found evidence to suggest that these fusions may occur in the majority of prostate cancer cases." (PMID 18694509, 2008). "The objective of the current study is initially to use our cohort of 429 conservatively managed prostate cancer cases to assess the potential clinical significance of ETV1 gene alterations and in parallel to assess the relative frequency of each of the known ETV1 fusion partners." (PMID 18594527, 2008). "Additionally, ETV1 is the only gene listed in the COSMIC database, and chromosomal translocations involving this gene have been implicated as causative factors in Ewing Sarcoma and prostate cancer." (PMID 40320296, 2025). "Thus, our results demonstrate for the first time in prostate cancer models a functional interaction between ETS transcription factors (ETV1 and ERG) and MET signalling that confers more aggressive properties and highlight a molecular signature characteristic of this combined action." (PMID 39374163, 2025). "We, and others, have identified both specific and shared downstream targets of ERG and ETV1 in prostate carcinomas, supporting the existence of targetable molecular pathways that may overcome the challenges in direct targeting ETS transcription factors as a therapeutic approach." (PMID 40808640, 2025).
prostate carcinoma (continued). "The transcription factors with whom β-DG interacts physically or functionally to modulate the cell division cycle or cell differentiation remain essentially unknown, with the exception of ETV1, a transcriptional regulator with an involvement in prostate cancer metastasis." (PMID 36494657, 2022). "A previous study revealed that AR could upregulate TWIST1 via ETV1 in prostate cancer." (PMID 33510354, 2021). "Studies have linked TMPRSS2 to prostate cancer via a chromosomal translocation resulting in the fusion of the TMPRSS2 promoter-enhancer with the Erythroblast Transformation Specific (ETS) transcription factors ETS-related gene (ERG) and ETS translocation variant 1 (ETV1)." (PMID 32974166, 2020). "In addition, zerumbone selectively inhibited the IL-6/JAK2/STAT3 pathway and blocked the prostate cancer-associated genes- cyclin D1, IL-6, COX2 (cytochrome c oxidase), and ETS Variant 1 (ETV1); thereby inducing cytotoxicity through G0/G1 cell cycle arrest and causing apoptosis." (PMID 30781671, 2019). "Furthermore, our data indicate that ETV1 may be needed for maximal TGF-β activity in prostate cancer cells." (PMID 31160676, 2019). "Indeed, many androgen-regulated genes have been identified and shown to be important in prostate cancer, including PSA (prostate specific antigen), hKLK2 (human kallikrein-2), TMPRSS2 (transmembrane protease, serine 2), ETV1 (Ets variant gene 1), and sGCα1 (soluble guanylyl cyclase α1)." (PMID 28859127, 2017). "Using a panel of prostate cancer cell lines we found co-overexpression of ETV1 and ETV4 in two cell line models of advanced prostate cancer (MDA-PCa-2b and PC3) and questioned whether these PEA3 family members would cooperate in the acquisition of oncogenic properties or show functional redundancy." (PMID 25595908, 2015). "After carrying out in vitro experiments, we demonstrated that ETV1 and ERG transcription factors induced migration and invasion capacities in PC3M and PC3 prostate cancer cells as well as HGF stimulation." (PMID 39374163, 2025). "Using the PC3M and PC3 hormone‐independent prostate cancer cell lines, we explored the regulatory interaction between MET signalling and ETV1/ERG activity and demonstrated a reciprocal action link." (PMID 39374163, 2025). "Collectively, our results identify a novel, ETV1‐dependent, oncogenic pathway in prostate cells and highlight the potential therapeutic outcome of coinhibition of EGFR and STAT3 in prostate carcinomas with ETV1 overexpression." (PMID 40808640, 2025). "ETV1 and ERG fusions are well documented in prostate cancer and are present throughout disease stages, from initiation to metastasis spread." (PMID 39374163, 2025). "ETV1 and ERG fusions are present throughout the progression of prostate cancer, while MET, whose expression is repressed by the androgen receptor, appears mainly in advanced PCa and bone metastasis." (PMID 39374163, 2025). "To investigate the interplay between ETV1, ERG and MET signalling, we selected prostate cancer cell lines expressing MET endogenously, the PC3M and PC3." (PMID 39374163, 2025). "Meanwhile, miR-129-5p binds downstream DLX1, ETV1 and CAMK2N1 targets to mediate the progression of prostate cancer and affect the biological functions of cancer cells." (PMID 39003446, 2024). "HERV-induced chromosomal translocation is another oncogenic mechanism as has been shown in prostate cancer, where HERV-K_22q11.3 is fused to the oncogene E26 transformation-specific family gene ETV1." (PMID 37296931, 2023). "In prostate cancer, numerous gene fusions are found involving different ETS transcription factors such as Erg, Etv1, Etv4, and Etv5." (PMID 37686260, 2023). "Fortunately, cancer driver genes in prostate cancer, ERG, ETV1, ETV4, SPOP, and FOXA1, have been identified and their roles have been proved through basic and clinical research." (PMID 36579559, 2022).
prostate carcinoma (continued). "In prostate cancer, the ETS family members ERG as well as ETV1 are commonly rearranged and ectopic ERG expression by TMPRSS2-ERG fusion blocks NE differentiation." (PMID 34121659, 2021). "More recently, co-expression of ETV1 and ETV4 was found in PC-3 and MDA-PCa-2b prostate cancer cell lines, representing models of advanced disease." (PMID 33634124, 2021). "Collectively, these data suggest that AR induces expression of Twist1 via ETV1, leading to enhanced EMT and migration of prostate cancer cells." (PMID 32296610, 2020). "Whilst this manuscript was under review, it has been reported that indeed ETV1, ETV4 and ETV5 can transcriptionally upregulate TAZ in prostate cancer cells." (PMID 30952872, 2019). "In prostate cancer, three members of the ETS family (ERG, ETV1, and ETV4) are commonly overexpressed due to chromosomal translocations." (PMID 30603056, 2018). "We found that 79 of 20261 genes showed marked over-expression (outliers) in certain tumor samples, including 3 previously reported prostate cancer genes (ERG, ETV1, and SPINK1)." (PMID 28027300, 2016). "The discovery and functional validation of recurrent gene fusions of 5 Ets factor genes (ETV1, ETV4, ETV5, ERG, Fli1) in prostate cancer highlights the relevance of Ets transcription factors as oncogenes in prostate cancer." (PMID 26885618, 2016). "We show that overexpression of these GRPR targets is restricted to prostate carcinomas harbouring ERG and/or ETV1 rearrangements, establishing their potential as therapeutic targets for these particular molecular subsets of the disease." (PMID 26316886, 2015). "Conversely, some lineage-specific genes are seen to serve as 5′ partners across multiple different 3′ genes; for example, TMPRSS2 and SLC45A3 in prostate cancer have been observed as 5′ partners of ERG, ETV1, ETV4, ETV5, BRAF, and ELK4." (PMID 26684754, 2015). "ETS family gene fusions, primarily including ERG (and less frequently, ETV1, ETV4, ETV5 or FLI1), are found in approximately 50 % of prostate cancers, the most common fusion being TMPRSS2-ERG." (PMID 26684754, 2015). "We recently reported mouse models of prostate cancer that recapitulate the most frequent ETS gene fusions, TMPRSS2-ERG and TMPRSS2-ETV1, with ectopic ERG or ETV1 expression from the endogenous Tmprss2 promoter." (PMID 25780911, 2015). "ERG and ETV1: These two genes belong to the ETS transcription factors and have been found to be overexpressed in prostate cancer tissues." (PMID 24282788, 2013). "The fusion of the TMPRSS2 gene with E-twenty six (ETS) family genes like ETV1, ERG and ETV4 occurs in up to 70% of all prostate cancers and is therefore a specific biomarker for prostate cancer diagnostics." (PMID 23341502, 2013). "Recurrent gene fusions involving several members of ETS transcription factor family (ERG, ETV1, ETV4 or ETV5) were found to be the most frequent genetic alterations in prostate cancer, which can be detected in as many as 50%–70% of prostate cancer samples." (PMID 23852643, 2013). "While the TMPRSS2:ETV1 fusion is rare and occurs in 1–10% of prostate cancers, the TMPRSS2:ERG fusion is present in roughly half of prostate cancers and is the most common genetic aberration so far described in prostate cancer." (PMID 23957008, 2013). "These aggressive prostate cancers fuse the promoter of TMPRSS2, an androgen responsive gene, to an ETS family transcription factor, such as ETV1 or ERG, both of which have also been identified in joining to EWS in ESFT to form an oncogenic fusion protein." (PMID 22383402, 2012). "Since ERG and ETV1 belong to the same class of ETS factors as FLI1, we tested the ability of YK-4-279 to inhibit biological functions of ERG and ETV1 proteins in prostate cancer." (PMID 21559405, 2011). "Especially TMPRSS2 fuses with ERG and Ets family genes such as ETV1, ETV4 and ETV5 in prostate cancers." (PMID 21347291, 2011).